CXCL12 (C-X-C motif chemokine ligand 12)
Diseases named in the same sentence as CXCL12 in open-access papers (continued):
Sharing a sentence is not in itself a finding about the gene and the disease.
ocular adnexal lymphoma (1 paper, 2015). A non-Hodgkin lymphoma arising from the conjunctiva, lacrimal gland, lacrimal drainage apparatus, eyelids, or other orbital tissues around the eye. "In contrast, the malignant B cells in ocular adnexal lymphomas (10 FL, 9 DLBCL, 4 MCL and 28 MZL) expressed a profile of molecules suggesting a dynamic process of trafficking involving not only tissue retention but also egress via S1PR3 and homing back to extranodal sites via CXCR4/CXCL12 and α4." (PMID 25938000, 2015).
ocular toxoplasmosis (1 paper, 2023). Ocular toxoplasmosis is an infection in the eye caused by the parasite, Toxoplasm a gondii. "In another study, patients with ocular toxoplasmosis displayed high levels of IFN-induced chemokines CXCL9 and CXCL10 and circulating chemokines CCL25, CCL11, CXCL12, CXCL13, and CCL2." (PMID 36755348, 2023).
odontogenic cyst (1 paper, 2022). A cyst in the jaw that arises from tissues of tooth development. "Chemokine CXCL12 and its receptor CXCR4 participate in several physiologic and pathologic processes, but there is a lack of information about the role of these proteins in the pathogenesis of odontogenic cysts, as the available data are restricted to radicular cysts." (PMID 35582358, 2022).
onchocerciasis (1 paper, 2009). Onchocerciasis is a form of filariasis, caused by the parasitic worm Onchocerca volvulus, transmitted by the black fly. "The neovascularisation was associated with a particular pattern of angio/lymphangiogenic factors in nodules of onchocerciasis patients, characterized by the expression of CXCL12, CXCR4, VEGF-C, Angiopoietin-1 and Angiopoietin-2." (PMID 20011036, 2009).
ovarian serous carcinoma (1 paper, 2023). "A high proportion of CXCL12 + positive immune cells in primary ovarian serous carcinoma correlated significantly with chemosensitivity (p = 0.005), overall survival (p = 0.021), and longer recurrence-free survival (p = 0.038)." (PMID 37966614, 2023).
papilloma (1 paper, 2015). A benign epithelial neoplasm that projects above the surrounding epithelial surface and consists of villous or arborescent outgrowths of fibrovascular stroma. "In addition to EMT, we have observed that Nanog-overexpressing papillomas upregulate genes associated to cancer stem features, most notably, Cxcl12/Sdf-138, Lgr539 and Pdgfra40." (PMID 25988972, 2015). "A number of genes related to cancer stem cells were validated by qRT-PCR, including Cxcl12/Sdf-1, Pdgfra, Lgr5, Lrg1, Pecam1/CD31, H19 and Src2, which were all significantly upregulated in Nanog-papillomas and Nanog-SCCs relative to control papillomas." (PMID 25988972, 2015).
pemphigoid (1 paper, 2024). "In an enzyme-dependent role, the accumulation of CXCL12, a substrate of DPP-4, may be involved not only in the pathogenesis of pemphigoid but also in renal disease." (PMID 38055184, 2024).
placenta previa (1 paper, 2023). "In our study, we observed that there was a CXCL12 level in the placental tissues of puerperae with placenta previa, and elevated CXCL12 induced the HTR8/SVneo cell activities." (PMID 37589008, 2023). "Additionally, the levels of CXCR4, CXCR7, and CXCL12 in placental tissues of patients with placenta previa exhibited a significant difference in the cases of scar uterus, history of pelvic inflammation, history of cesarean section, and history of abortion." (PMID 37589008, 2023). "CXCL12, CXCR4, and CXCR7 are highly expressed in placental tissues of patients with placenta previa and induce the biological activities of HTR8/SVneo cells." (PMID 37589008, 2023). "CXCL12, CXCR4, and CXCR7 expression was elevated in placental tissues from patients with placenta previa." (PMID 37589008, 2023). "The relationship between the expression levels of CXCL12, CXCR4, and CXCR7 mRNA in placental tissues of the patients with placenta previa and their clinical parameters was analyzed." (PMID 37589008, 2023). "This research was designed to probe the expression of chemokine CXCL12 and its receptors CXCR4 and CXCR7 in placental tissues of patients with placenta previa and the effect of CXCL12/CXCR4/CXCR7 axis on the biological functions of human trophoblast cells." (PMID 37589008, 2023). "The IHC results indicated that the expression of CXCL12, CXCR4, and CXCR7 in placenta tissues of patients with placenta previa was higher than those of normal puerperae." (PMID 37589008, 2023). "This research was designed to probe the levels of the chemokine CXCL12 and the receptors CXCR4/CXCR7 in the placental tissues of patients with placenta previa and their effects on the biological functions of human trophoblast cells." (PMID 37589008, 2023). "CXCL12, CXCR4, and CXCR7 expression in placental tissue from patients with placenta previa and healthy puerperae was detected." (PMID 37589008, 2023). "The CXCL12/CXCR4/CXCR7 axis is of great significance in various physiological and pathological conditions, but their functions in placenta previa remain largely unknown." (PMID 37589008, 2023). "CXCL12, CXCR4, and CXCR7 levels in placental tissues were evaluated by IHC, and the findings demonstrated that brownish-yellow staining was seen in the cytoplasm of both syncytiotrophoblasts and cytotrophoblasts in the placental tissues of pregnant women with placenta previa." (PMID 37589008, 2023).
Pleural effusion (1 paper, 2012). The presence of an excessive amount of fluid in the pleural cavity. "CXCL12 levels are also increased specifically in tuberculous pleurisy pleural effusions, although the mechanism and function of this increase have not been demonstrated." (PMID 23028695, 2012). "CXCL12 was highly expressed in the TP pleural effusions but not after stimulation, which may result from the kinetics of cytokine production or from a separate production pathway." (PMID 23028695, 2012).
pleural tumor (1 paper, 2023). "Economidou and associates showed that high CXCL12 levels in the pleural effusion of patients with NSCLC are associated with pleural tumor dissemination." (PMID 37227446, 2023).
pulmonary atresia (1 paper, 2018). "In summary, while all Cxcl12 and Cxcr4 (not shown) constitutively null embryos had a membranous VSD at E15.5 we found no examples of CAT, IAA-B or retro-oesophageal RSA, nor did we see any examples of pulmonary atresia (part of the tetralogy of Fallot spectrum)." (PMID 30408103, 2018).
RSV bronchiolitis (1 paper, 2025). "The results showed that CXCL12 was an independent risk factor for the severity of RSV bronchiolitis in children (P < 0.05)." (PMID 41360931, 2025). "In children with RSV bronchiolitis, plasma CXCL12 levels showed a positive correlation with the length of hospital stay and platelet count (r = 0.534 and 0.355; P < 0.001)." (PMID 41360931, 2025). "In children with RSV bronchiolitis, plasma CXCL12 levels showed a positive correlation with disease severity (r = 0.580; P < 0.001), indicating that higher plasma CXCL12 levels were associated with more severe RSV bronchiolitis." (PMID 41360931, 2025). "Similarly, plasma CXCL12 levels were significantly elevated in the RSV bronchiolitis group compared to the control group [2261.05 (1737.67, 3263.10)pg/mL vs.1061.29 (683.40, 1846.43) pg/mL; P < 0.001]." (PMID 41360931, 2025). "CXCL12 and CXCL13 may serve as biomarkers for assessing RSV bronchiolitis severity and predicting recurrence, aiding early clinical evaluation and prognosis." (PMID 41360931, 2025). "A CXCL12 level exceeding 2658.93 pg/ml indicates progression to severe viral pneumonia, whereas a CXCL13 level above 306.448 pg/ml predicts recurrent wheezing in children with RSV bronchiolitis." (PMID 41360931, 2025).
salivary gland tumors (1 paper, 2025). "In patients with salivary gland tumors (WT and PA), various chemokines have been determined, including CCL28, CXCL10, CXCL12, CCL18, and CXCL1, as well as pro-inflammatory cytokines such as IL-1β, IL-6, IL-4, IL-17, and IL-33." (PMID 40807046, 2025).
schistosomiasis (1 paper, 2020). An infectious disease caused by parasitic trematodes of the genus Schistosoma that colonize human blood vessels and release eggs that can cause granulomatous reactions leading to acute (swimmer's itch or acute schistosomiasis syndrome) or chronic disease. "Our findings uncovered a previously unappreciated role of Tfh cells in promotion of the development of liver granuloma in schistosomiasis, making Tfh‐CXCL12‐eosinophil axis a potential target for intervention of schistosomiasis." (PMID 31912645, 2020). "In summary, our study reveals a novel role of Tfh cells in controlling eosinophil migrating and provides additional insights into granuloma formation during S japonicum infection, making Tfh‐CXCL12‐eosinophil axis a potential target for treating schistosomiasis." (PMID 31912645, 2020).
scrub typhus (1 paper, 2021). Scrub typhus is a rare dust mite-borne infectious disease caused by the Orientia tsutsugamushi bacterium and characterized clinically by an eruptive fever which is potentially serious. "Concurrently, a significant reduction in type 2- or tissue healing-related genes, including Cxcl12 (p < 0.05), Ccrl1 (p < 0.0001), Mrc-1 (p < 0.0001), and Ahr (p < 0.0001), provided additional evidence for skewed type 1, but absent type 2, immune responses in our model of severe scrub typhus." (PMID 34320039, 2021).
sialadenitis (1 paper, 2021). Sialadenitis is an infection of the salivary glands. "Although further studies are needed to elucidate the mechanisms underlying the overexpression of CXCL13 and CXCL12 in epithelial cells, the present results indicate that the CD153 vaccine is also effective for preventing age- and SS-related sialadenitis." (PMID 33669065, 2021).
sickle cell disease (1 paper, 2017). Sickle cell anemias are chronic hemolytic diseases that may induce three types of acute accidents: severe anemia, severe bacterial infections, and ischemic vasoocclusive accidents (VOA) caused by sickle-shaped red blood cells obstructing small blood vessels and capillaries. "Our findings suggest CXCL12 as a putative marker that could mediate a possible MTX-induced limitation of ischemia–reperfusion damage in sickle cell disease." (PMID 28638723, 2017).
skin aging (1 paper, 2024). The gradual irreversible changes in structure of skin that occur as a result of the passage of time.. "Wound closure of the skin is a medical problem related to skin aging, which is achieved by transforming lactobacilli into plasmids encoding CXCL12." (PMID 38612608, 2024). "CXCL12 can increase the proliferation of dermal cells and macrophages to enhance wound closure when administered locally to wounds of mice, and accelerating wound healing can improve bioavailability and prevent skin aging." (PMID 38612608, 2024).
status epilepticus (1 paper, 2010). Status epilepticus is defined as a continuous seizure lasting more than 30 min, or two or more seizures without full recovery of consciousness between any of them. "Our data corroborate earlier studies demonstrating that CXCL12 expression is increased following status epilepticus, but this increase may be transient without spontaneous recurrent seizures." (PMID 21209827, 2010).
testicular cancer (1 paper, 2019). A primary or metastatic malignant neoplasm that affects the testis. "CXCL12 expression was analyzed on a tissue microarray consisting of 750 tissue cores of different histological tumor components, Germ cell neoplasia in situ (GCNIS) and adjacent normal tissue of 263 testicular cancer patients using a semi-quantitative score." (PMID 31412792, 2019).
Thrombocytosis (1 paper, 2023). Increased numbers of platelets in the peripheral blood. "This cell-to-cell contact is dependent on binding of the chemokine-receptor CXCR4 to its ligand CXCL12, and so it is conceivable that neutrophilia can exacerbate thrombocytosis in ET." (PMID 37051288, 2023).
thromboembolic disease (1 paper, 2020). "Taking our results into account as a whole, the synergistic effect of CXCL12 and collagen mediated, at least in part, via the p38 MAPK pathway might be one of therapeutic targets for the prevention of atheroprogression and thromboembolic disease in patients strongly expressing CXCL12." (PMID 33119719, 2020).
viral meningitis (1 paper, 2019). Inflammation of the membranes surrounding the brain and spinal cord due to a viral infection. "CX3CL1 and CXCL12 were only found elevated in viral meningitis." (PMID 31727097, 2019).
Wilms tumor (1 paper, 2016). An embryonal neoplasm characterized by the presence of epithelial, mesenchymal, and blastema components. "The aim of the present study was to analyze rs3761548 and rs2232365 FOXP3 polymorphisms, as well as evaluate rs1801157 CXCL12 polymorphism in Wilms’ tumor samples." (PMID 27830498, 2016).
tumor (2,986 papers, 2002 to 2026). "Temporal elevation of CXCR4 expression on tumor‐infiltrated CD8+ T cells promoted their migration toward CXCL12‐expressing cancer‐associated fibroblast (CAFs) high‐density regions, which are distant from cancer cells." (PMID 41257391, 2026). "The amplitude of the Cxcr4 expression rhythm was more pronounced in tumor‐infiltrated T cells than in those from the spleen and was associated with time‐dependent changes in their migration toward CXCL12‐expressing cancer‐associated fibroblasts (CAFs)." (PMID 41257391, 2026). "Shuhai Chen and colleagues reported that CAFs promote M2 polarization of tumor-associated macrophages (TAMs) via CXCL12, leading these TAMs to secrete PAI-1." (PMID 41601623, 2026). "These iCAFs represent the predominant source of CXCL12, which plays a critical role in tumor-associated macrophage recruitment, with elevated CXCL12 levels correlating with poor prognosis and increased macrophage infiltration." (PMID 40940870, 2025). "By pooling data from ten studies with 1,361 patients, we found that patients with high tumor CXCL12 expression had a significantly higher risk of mortality compared to those with low expression." (PMID 40481962, 2025). "The pooled results of two studies showed that a high tumor expression of CXCL12 was associated with poorer PFS in patients with GC (HR: 1.52, 95% CI 1.05–2.20, p = 0.03) with no significant heterogeneity (p for Cochrane Q test = 0.76; I2 = 0%)." (PMID 40481962, 2025). "Subsequently, SIRT1 regulates the migration of tumor-associated macrophages (TAMs) through the CXCR4/CXCL12 pathway, which inhibits the proliferation and activity of CD8+ T cells." (PMID 40567502, 2025). "The activation of the CXCR4/CXCL12 axis was shown to upregulate a series of miRNAs that interact with tumour associated macrophages at the invasive fronts of tumours, resulting in M2 polarisation of these macrophages." (PMID 39982274, 2025). "The association between tumor expression of CXCL12 and the survival outcomes of patients with GC was evaluated using univariate analysis in six studies, and with multivariate analysis in four studies." (PMID 40481962, 2025). "On the other hand, we found that tumor niches expressing high levels of cytokeratins and CXCL12 are associated with better outcomes, lower tumor grade, and the clinically defined HR+/HER2− subtype." (PMID 40182181, 2025). "The CXCL12 expression level is negatively correlated with tumor grade, and its high expression is associated with improved prognosis and overall survival." (PMID 41445742, 2025). "Tumor cells and other cell types such as cancer-associated fibroblasts or stromal cells in the tumor secrete S1P and CXCL12, which provide them a survival and proliferation advantage." (PMID 40155684, 2025). "The pooled results showed that overall, a high tumor expression of CXCL12 was associated with poorer OS in patients with GC (HR: 1.85, 95% CI 1.51–2.26, p < 0.001)." (PMID 40481962, 2025). "The treatment decreased tumor perfusion and produced radiographic responses in 90% of patients, with higher CXCL12 levels associated with better progression-free survival." (PMID 41245487, 2025). "A previous study indicated that CAFs in OSCC secrete CXCL12, which attracts monocytes and promotes their differentiation into tumor-associated M2 macrophages via the CXCL12/CXCR4 pathway." (PMID 40805285, 2025). "CXCL12 expressed by cancer-associated fibroblasts then banded to CXCR4 on tumor cells and induced epithelial-mesenchymal transformation, ultimately promoting metastasis to secondary tumor sites." (PMID 41347146, 2025). "Both tumor cells and tumor-associated fibroblasts have the capacity to secrete CXCL12, which serves to attract tumor cells, immune cells, and vascular endothelial cells that express CXCR4, thereby facilitating their migration toward the tumor site." (PMID 41394878, 2025).